NAB2 (NGFI-A binding protein 2)
Description:
Acts as a transcriptional repressor for zinc finger transcription factors EGR1 and EGR2. Isoform 2 lacks repression ability (By similarity).
Synonyms: MADER
Tractability: PROTAC: UniProt records ubiquitination sites on it; ubiquitination databases record sites on it; its protein half-life has been measured.
Gene: Protein-coding gene on chromosome 12 (57,089,014 to 57,095,476, forward strand). Ensembl gene ENSG00000166886.
Subcellular location: Nucleus
Subcellular location (Human Protein Atlas): Cytosol; Nucleoplasm
Pathways (Reactome):
Developmental Biology: EGR2 and SOX10-mediated initiation of Schwann cell myelination
Signal Transduction: NGF-stimulated transcription
Gene Ontology:
Molecular function: identical protein binding; protein binding; transcription coregulator activity; transcription corepressor activity
Biological process: negative regulation of transcription by RNA polymerase III; regulation of DNA-templated transcription; negative regulation of DNA-templated transcription
Cellular component: nucleoplasm; nucleus
Genetic constraint (gnomAD): Loss-of-function variants: 9 observed, 38.94 expected, observed/expected ratio (o/e) 0.23, 90% interval 0.14 to 0.4. The synonymous counts are far from expectation, so gnomAD's model fits this gene poorly and the ratio says little. Missense variants: 514 observed, 677.91 expected, observed/expected ratio (o/e) 0.76, 90% interval 0.7 to 0.82. Synonymous variants: 342 observed, 275.92 expected, observed/expected ratio (o/e) 1.24, 90% interval 1.13 to 1.36.
Cancer hallmarks: angiogenesis (suppresses)
Homologues: Orthologues: chimpanzee NAB2 (100% identical), macaque NAB2 (99% identical), dog NAB2 (98% identical), pig NAB2 (98% identical), guinea pig NAB2 (98% identical), rat Nab2 (97% identical), mouse Nab2 (96% identical), rabbit NAB2 (93% identical), tropical clawed frog nab2 (52% identical), zebrafish nab2 (45% identical), Drosophila melanogaster nab (30% identical), Caenorhabditis elegans mab-10 (24% identical). Paralogues in human: NAB1 (39% identical).
Diseases named in the same sentence as NAB2 in open-access papers:
NAB2 is named in the same sentence as 47 diseases in open-access papers, as found by Europe PMC text mining. Sharing a sentence is not in itself a finding about the gene and the disease. The quoted sentences say what the papers report.
solitary fibrous tumor (21 papers, 2015 to 2026). Solitary fibrous tumor (SFT) represents a diverse group of ubiquitous rare spindle cell neoplasms that may be benign or malignant and that most frequently arises from the pleura and peritoneum and rarely from other sites such as head and neck, liver and skeletal muscle. "In 2013, it was discovered that nearly all solitary fibrous tumors have a version of a hallmark intrachromosomal fusion gene between NAB2 and STAT6 on chromosome 12." (PMID 41166819, 2025). "The NAB2 exon 4–STAT6 exon 2–3 variant seems to be most often found in tumors resembling the conventional ‘solitary fibrous tumor,’ while tumors with NAB2 exon 6–STAT6 exon 16–17 exhibit morphologic features consistent with what was previously considered ‘hemangiopericytoma’." (PMID 30584643, 2019). "Solitary fibrous tumor (SFT) is a rare mesenchymal tumor defined by the NGFI-A binding protein 2 (NAB2)-signal transducer and activator of transcription 6 (STAT6) fusion gene and rarely arises in the sinonasal tract." (PMID 41431481, 2025). "De Novo Analysis, which identifies SVs > 500 bp, detected additional alterations in one tumor, corresponding to a solitary fibrous tumor with a NAB2::STAT6 fusion." (PMID 40141463, 2025). "Solitary fibrous tumor (SFT) represents a fibroblastic neoplasm exhibiting NAB2::STAT6 gene rearrangement, displaying diverse clinical manifestations, spanning from benign to malignant." (PMID 38239634, 2023). "Solitary fibrous tumor (SFT) is a fibroblastic neoplasm characterized by NAB2::STAT6 gene fusions and can occur in various anatomical sites, displaying a wide morphological spectrum." (PMID 38239634, 2023). "The 29 tumors harboring NAB2 exon 4–STAT6 exon 2–3 or the 10 with “other fusions” were more likely to be solitary fibrous tumors (n = 24, n = 8) compared to malignant solitary fibrous tumors (n = 5, n = 2)." (PMID 30584643, 2019). "Solitary fibrous tumor (SFT) is a fibroblastic neoplasm with NAB2 and STAT6 gene fusion as well as STAT6 nuclear expression." (PMID 42256992, 2026). "While NAB2:STAT6 fusions are common in solitary fibrous tumors (SFT), we report this event for the first time in a newly diagnosed, secondary-type GBM or any other non-SFT." (PMID 26817999, 2016). "(c) Most abundant gene fusion present in all solitary fibrous tumors (SFTs) in FFPE RNA-seq, NAB2-STAT6 with exons 1–4 of NAB2 and exons 2–22 of STAT6." (PMID 40875449, 2025). "Patients suffering from solitary fibrous tumor and hemangiopericytomas present an intrachromosomal fusion between STAT6 and NAB2 genes, leading to the constitutive activation of NAB2." (PMID 41409600, 2025). "Solitary fibrous tumor (SFT) is a fibroblastic neoplasm characterized by distinctive thin-walled, branching, staghorn-shaped vessels and the NAB2::STAT6 fusion gene." (PMID 40002892, 2025). "One tumor diagnosed initially as undifferentiated round cell sarcoma harbored NAB2::STAT6 fusion and was reclassified as an aggressive metastatic solitary fibrous tumor." (PMID 38440233, 2024). "One tumor diagnosed initially as undifferentiated round cell sarcoma harbored NAB2::STAT6 fusion and was reclassified as solitary fibrous tumor (patient #32)." (PMID 38440233, 2024). "A recurring and nonrandom fusion of two genes has been recently identified in solitary fibrous tumor and involves the NGFI-A-binding protein 2 (NAB2) and STAT6 genes, both located at chromosomal region 12q13." (PMID 27672467, 2016). "The fibroblastic cells were positive for STAT6 and sequencing analysis revealed the gene fusion between NAB2 exon 4 and STAT6 exon 2, with which the final diagnos is of solitary fibrous tumor was achieved." (PMID 26425382, 2015). "HPC has been found to share inversions on the long arm of chromosome 12 (12q13) and a fusion of the NAB2 and STAT6 genes with the solitary fibrous tumor (SFT)." (PMID 40135019, 2025).
solitary fibrous tumor (continued). "Fusion genes of the NGFI-A binding protein-2 signal transduction and transcriptional activator-6 (NAB2-STAT6) were detected early in SFT (solitary fibrous tumor) and hemangiopericytoma (HPC)." (PMID 39030639, 2024).
prostate carcinoma (6 papers, 2007 to 2023). A carcinoma that arises from epithelial cells of the prostate gland. "Upregulation of EGR-1 and loss of its repressor NAB2 contribute to increasing levels of EGR-1 activity in prostate cancer." (PMID 36233659, 2022). "EGR1 is overexpressed in prostate cancer, while NAB2 expression is reduced in most prostate cancer samples, which suggest that repression of EGR1 activity promote prostate cancer." (PMID 36979412, 2023). "EGR1 overexpression is well correlated with the loss of its co-repressor NAB2 in primary prostate carcinoma; this unbalance between EGR1 and NAB2 expression results in high EGR1 transcriptional activity in prostate carcinoma cells." (PMID 30925677, 2019). "For example, NAB2 is often downregulated in prostate cancer but upregulated in malignant melanoma." (PMID 17207284, 2007). "The NAB2 (NGF-1A binding protein), which represses the transcriptional activity of EGR-1, is down-regulated in prostate carcinomas." (PMID 36233659, 2022). "In addition, NuRD complex with NAB2, a co-repressor of the early growth response (EGR) family of transcriptional transactivator, repress EGR activities that promote progression of prostate cancer." (PMID 31040906, 2019).
Intellectual disability (4 papers, 2019 to 2023). "The Drosophila polyadenosine RNA binding protein Nab2, which is orthologous to a human protein lost in a form of inherited intellectual disability, controls adult locomotion, axon projection, dendritic arborization, and memory through a largely undefined set of target RNAs." (PMID 37458420, 2023). "This hypothesis is significant given that very few Nab2-target mRNAs are known and the Nab2 human ortholog ZC3H14 is lost in an inherited form of recessive intellectual disability." (PMID 32817074, 2020). "Importantly, mutations in the gene encoding the human Nab2 orthologue ZC3H14 and cause intellectual disability." (PMID 30578643, 2019). "Here, we uncover a role for Drosophila Nab2, an evolutionarily conserved RBP with links to human inherited intellectual disability, in cell-autonomous restriction of dendrite branching and projection among ddaC body-wall sensory neurons." (PMID 35471546, 2022).
mesenchymal neoplasm (4 papers, 2025 to 2026). "PURPOSE: Solitary fibrous tumour (SFT) is a rare mesenchymal neoplasm molecularly defined by the NAB2::STAT6 gene fusion (GF), an aberrant transcriptional regulator whose functions beyond EGR1 activation remain incompletely understood." (PMID 41665771, 2026).
hemangiopericytoma (3 papers, 2019 to 2025). An antiquated term that refers to benign or malignant mesenchymal neoplasms characterized by the presence of neoplastic spindle-shaped to round cells arranged around thin-walled branching vascular spaces. "Both the SFT and hemangiopericytoma (HPC) showed 12q13 inversion and NAB-2 and STAT-6 gene fusion." (PMID 35641960, 2022).
melanoma (3 papers, 2007 to 2024). A malignant, usually aggressive tumor composed of atypical, neoplastic melanocytes. "Egr2 and Egr3 can induce the expression of Nab2 in melanoma cells." (PMID 38666929, 2024). "One example of epigenetic dysregulation in melanoma is the NAB2/EGR system (NAB2: NGFI-A binding protein 2, NGFI-A: nerve growth factor-induced protein A, EGR: early growth response protein) which is associated with several malignancies, especially in melanoma." (PMID 38001098, 2023).
schizophrenia (3 papers, 2018 to 2022). A major psychotic disorder characterized by abnormalities in the perception or expression of reality. "Direct support for possible association between NAB2 and schizophrenia comes from the 2014 Schizophrenia Working Group of the Psychiatric Genomics Consortium GWAS." (PMID 29520222, 2018). "EGR3 interacts in regulatory feedback loops with other EGR-family genes in the immune system, including EGR1, EGR2, EGR4 and NAB2, each of which maps to GWAS loci for schizophrenia." (PMID 35941129, 2022). "The regulatory relationships with schizophrenia-associated EGRs (EGR1 and EGR3) suggest a role for NAB2 in neuropsychiatric illness." (PMID 29520222, 2018). "Despite the paucity of published work on the role of NAB2 in the brain, the regulatory relationships between NAB2, EGR1 and EGR3 link this gene not only to other specific schizophrenia-associated genes, but also to the proposed pathway for illness association." (PMID 29520222, 2018). "HRH1, targeted by cinnarizine, was predicted to interact with the schizophrenia gene NAB2." (PMID 31481665, 2019). "EGR3 binds to NAB2 to co-regulate expression of target genes, and is involved in co-regulatory feedback relationships with EGR1, as well EGR1, EGR2 and EGR3 can regulate NAB2 expression, demonstrating a functional interaction of both of these schizophrenia associated genes in the proposed pathway." (PMID 29520222, 2018). "Additional proteins implicated in risk for schizophrenia, but that have not yet been reported to affect LTD, interact with this pathway either as upstream activators (e.g., NRG1) or as transcriptional regulators (e.g., EGR1 and NAB2)." (PMID 29520222, 2018).
Ewing sarcoma (2 papers, 2007 to 2022). A small round cell tumor that lacks morphologic, immunohistochemical, and electron microscopic evidence of neuroectodermal differentiation. "Interestingly, NAB2 is downregulated in other tumors including Non-Hodgkin lymphoma and Neuroblastoma but we observed moderate to high upregulation in a few cases of Ewing sarcoma and Rabhdomyosarcoma, suggesting that NAB2 might be mutated in these tumors." (PMID 17207284, 2007). "Interestingly, a search in GEO profiles (Gene Expression Omnibus, NCBI) also showed a moderate expression of NAB2 in few cases of Ewing sarcoma (GPL1977 1934)." (PMID 17207284, 2007).
head and neck squamous cell carcinoma (2 papers, 2019). A squamous cell carcinoma that arises from any of the following anatomic sites: lip and oral cavity, nasal cavity, paranasal sinuses, pharynx, larynx, and salivary glands. "Therefore, we evaluated how the NAB2-mediated suppression of EGR1 facilitates head and neck squamous cell carcinoma (HNSCC) cancer progression, in association with Sp1, which competes with EGR1 as a transcriptional regulator." (PMID 30845713, 2019).
scleroderma (2 papers, 2009 to 2019). Scleroderma is a rare autoimmune connective tissue disorder characterized by abnormal hardening of the skin and, sometimes, other organs. "Previous data demonstrated that ectopic expression of NAB2 in normal fibroblasts of Scleroderma abrogated TGF-β-induced stimulation of collagen synthesis." (PMID 30893927, 2019). "In marked contrast, very strong and uniform Nab2 immunostaining was evident in each scleroderma skin biopsy." (PMID 19888474, 2009). "Skin biopsies from patients with scleroderma were characterized by markedly elevated Nab2 expression, localized primarily in the nuclei of epidermal keratinocytes and cells lining dermal appendages." (PMID 19888474, 2009). "We found a marked overexpression of Nab2 in scleroderma skin biopsies, where Nab2 was localized to epithelial cells, with only scant expression in fibroblastic cells in the dermis." (PMID 19888474, 2009). "Expression of Nab2 was markedly up-regulated in skin biopsies from patients with scleroderma, and was localized primarily to epidermal keratinocytes." (PMID 19888474, 2009). "The present results show that while Nab2 expression was highly elevated in scleroderma skin biopsies, in contrast to Egr-1, it was localized almost exclusively to the epidermis and epithelial cells lining dermal appendages, whereas dermal fibroblasts showed scant Nab2 expression." (PMID 19888474, 2009). "Impaired Nab2 expression or function might contribute directly to the development or progression of fibrosis in scleroderma." (PMID 19888474, 2009). "Defective Nab2 expression or function in dermal fibroblasts might play a role in persistent fibrotic responses in scleroderma." (PMID 19888474, 2009). "While Nab2 expression was dramatically up-regulated in epithelial cells in scleroderma skin biopsies, consistent with activated TGF-β signaling in the fibrotic milieu, dermal fibroblasts from biopsies that were strongly immunopositive for Egr-1 and phospho-Smad2 showed a paucity of Nab2 expression." (PMID 19888474, 2009).
autism (1 paper, 2010). Persistent deficits in social interaction and communication and interaction as well as a markedly restricted repertoire of activity and interest as well as repetitive patterns of behavior. "The six candidate genes sequenced, CNTN1, FOXJ2, GRIN2B, NAB2, NELL2 and SRGAP1, were selected based on their putative functions, and their relationships to genes potentially involved in the pathology of language impairments, auditory processing deficits, autism and dyslexia." (PMID 20345892, 2010).
Bone Tumors (1 paper, 2025). "In the 2020 WHO Classification of Soft Tissue and Bone Tumors, SFT is categorized as an intermediate fibroblastic neoplasm with low metastatic potential, defined by the NGFI-A binding protein 2 (NAB2)-signal transducer and activator of transcription 6 (STAT6) gene fusion." (PMID 41431481, 2025).
chronic myeloid leukemia (1 paper, 2017). "We next tested for correlations between WT1 and NAB2 expression in sample sets of gene expression profiles of primary AML and CML (chronic myeloid leukemia) samples." (PMID 29152069, 2017).
glioma (1 paper, 2022). A benign or malignant brain and spinal cord tumor that arises from glial cells (astrocytes, oligodendrocytes, ependymal cells). "Four genes showed a higher fusion rate in OAs included NAB2 (0.4% vs. 4.2%) and STAT6 (0.4% vs. 2.9%) in soft tissue sarcoma and FGFR3 (0.4% vs. 3.1%) and TACC3 (0 vs. 3.0%) in glioma." (PMID 36433963, 2022).
leukemia (1 paper, 2017). A malignant (clonal) hematologic disorder, involving hematopoietic stem cells and characterized by the presence of primitive or atypical myeloid or lymphoid cells in the bone marrow and the blood. "Whether NAB2 is a potential therapeutic target in leukemia remains to be determined." (PMID 29152069, 2017).
liposarcoma (1 paper, 2024). A usually painless malignant tumor that arises from adipose tissue. "CDKN2A/B), amplifications (e.g. JUN in liposarcoma), fusion partners (e.g. PAX3/7::FOXO1 in rhabdomyosarcoma), breakpoint positions in fusions (e.g. NAB2::STAT6 in SFT) and the extent of segmental (i.e. sub-chromosomal arm) copy number changes (e.g. synovial sarcoma)." (PMID 38997407, 2024).
malaria (1 paper, 2021). Malaria is a serious and sometimes fatal disease caused by a parasite that commonly infects a certain type of mosquito which feeds on humans. "We first investigated the effects of nab2, tho4, npl3, gbp2 and sr1 deletion on the asexual development of malaria parasites." (PMID 34604117, 2021). "In this study, we focused on GBP2 and NAB2, which play important roles in the sexual and asexual development of malaria parasites, respectively, and examined their cellular localization." (PMID 34604117, 2021). "Therefore, to elucidate the quality control and export of mRNA by RNA-binding proteins, we focused on GBP2 and NAB2, which play important roles in the sexual and asexual development of malaria parasites, respectively." (PMID 34604117, 2021). "To determine whether NAB2 localizes to the inside of the nuclear membrane in malaria parasites, we generated a NAB2::mCherry strain expressing NUP205 fused to green fluorescent protein (GFP)." (PMID 34604117, 2021). "Our results imply that NAB2 and SR1 are essential for the asexual development of malaria parasites." (PMID 34604117, 2021). "Our findings imply that NAB2 and GBP2 are involved in nuclear mRNA export in malaria parasites." (PMID 34604117, 2021). "Nuclear poly(A) binding protein 2 (NAB2), THO complex subunit 4 (THO4), nucleolar protein 3 (NPL3), G-strand binding protein 2 (GBP2) and serine/arginine-rich splicing factor 1 (SR1) are involved in nuclear mRNA export in malaria parasites." (PMID 34604117, 2021). "NAB2 and SR1 were found to be essential for the survival of malaria parasites." (PMID 34604117, 2021). "In this study using the rodent malaria parasite, Plasmodium berghei, we found that NAB2 and SR1, but not THO4, NPL3 or GBP2, played essential roles in the asexual development of malaria parasites." (PMID 34604117, 2021). "SR1, but not NAB2, is localized to the nucleus and bound to RNAs in malaria parasites." (PMID 34604117, 2021). "We found that NAB2 and SR1, but not THO4, NPL3 or GBP2, played essential roles in the asexual development of malaria parasites." (PMID 34604117, 2021). "Δnab2 and Δsr1 mutants could not be generated, implying that NAB2 and SR1 are essential for the asexual development of malaria parasites." (PMID 34604117, 2021).
mesothelioma (1 paper, 2025). A usually malignant and aggressive neoplasm of the mesothelium which is often associated with exposure to asbestos. "(d) NAB2-STAT6 gene fusion in (NAB2 exons 1–6, STAT6 exons 17–22) present in TCGA SH A7BH, originally diagnosed mesothelioma." (PMID 40875449, 2025).
metastatic carcinoma (1 paper, 2019). A carcinoma which has spread from the original site of growth to another anatomic site. "Samples of primary HNSCC in oral mucosa and metastatic carcinoma in the lymph node were examined for NAB2 expression by immunohistochemistry." (PMID 30893927, 2019).
oral cancer (1 paper, 2020). "This study provides novelty by showing that mRNA levels of MAOB, NAB2, COL3A1, NPIPB4, CYP27A1, and SIAE were significantly reduced in the saliva of oral cancer patients." (PMID 31963366, 2020).